PCNA (proliferating cell nuclear antigen)
Diseases named in the same sentence as PCNA in open-access papers (continued):
Sharing a sentence is not in itself a finding about the gene and the disease.
acute pancreatitis (1 paper, 2024). An acute inflammatory process that leads to necrosis of the pancreatic parenchyma. "Immunohistochemical (IHC) staining of proliferating cell nuclear antigen (PCNA) indicated fewer proliferative cells in the pancreases of Reg4−/− mice than in Wt mice, particularly during acute pancreatitis." (PMID 38769308, 2024).
adenoid cystic carcinoma (1 paper, 2012). A malignant tumor arising from the epithelial cells.
adenomatous colonic polyps (1 paper, 2020). "We observed the increase in infiltration of inflammatory cells, a key feature of sporadic adenomatous colonic polyps with an increased number of Ki67-, CD45-, β-catenin-, proliferating cell nuclear antigen (PCNA)-, and F4/80-positive cells in the Chi/PA-attached Nudt7+/+ colon polyp." (PMID 32131398, 2020).
adrenocortical adenoma (1 paper, 2008). "When FHIT, Ki-67 and PCNA are all positive, adrenocortical adenoma is suggested." (PMID 18366613, 2008).
allergic rhinitis (1 paper, 2012). Inflammation of the nasal mucous membranes caused by an IgE-mediated response to external allergens. "In humans, PCNA-positive MCs have been observed in the nasal sub-epithelial and lamina propria layers in patients suffering allergic rhinitis." (PMID 22967751, 2012).
Alport syndrome (1 paper, 2021). A rare renal disease characterized by glomerular nephropathy with hematuria progressing to end-stage renal disease (ESRD), frequently associated with sensorineural deafness, and occasionally with ocular anomalies. "Intraglomerular PCNA-positive and periglomerular interstitial α-SMA-positive cells were decreased in metformin or losartan-treated Col4a5 G5X Alport syndrome mice." (PMID 33782421, 2021).
ameloblastic carcinoma (1 paper, 2013). A rare, cytologically malignant ameloblastoma that may metastasize. "When analyzing cell proliferation using PCNA, we found significant differences only among the ameloblastic carcinomas (93.3%) and the DA (p<0.05)." (PMID 23229269, 2013).
anal carcinoma (1 paper, 2010). "A single study has assessed the prognostic significance of PCNA in anal carcinoma, in which immunohistochemistry was used to analyse tumour samples obtained from 62 patients." (PMID 21063399, 2010).
anaplastic thyroid cancer (1 paper, 2016). "Both OB3 and leptin reduced PCNA expression significantly and increased the expression of c-Myc and MCL-1 slightly in anaplastic thyroid cancer cells." (PMID 27050378, 2016).
aneurysm (1 paper, 2019). Bulging or ballooning in an area of an artery secondary to arterial wall weakening. "Additionally, the number of PCNA-positive cells was increased in both groups, indicating growth of the neointima over the aneurysm orifice and disruption of intra-aneurysmal flow, further reducing the risk of aneurysmal recanalization." (PMID 31886218, 2019).
aortic atherosclerosis (1 paper, 2019). A atherosclerosis that involves the aorta. "After aortic chemerin gene was inhibited by adenovirus, aortic atherosclerosis induced by high-fat diet was significantly meliorated, serum levels of TNF-α and IL-1β decreased, mRNA and protein levels of NF-κBp65, PCNA, p-p38-MAPK, p-JNK, and p-ERK 1/2 decreased simultaneously." (PMID 31781638, 2019).
arteriopathy (1 paper, 2024). "Intimal, medial, and wall thickening of IgAN arteriopathy are associated with VEGF, MMP-9, PCNA, and ERK1/2." (PMID 39669374, 2024). "VEGF (0.35 ± 0.90), MMP-9 (0.38 ± 0.12), PCNA (0.43 ± 0.12), ERK1/2 (0.31 ± 0.11), and NF-κB (0.37 ± 0.14) were the highest in IgAN with arteriopathy group." (PMID 39669374, 2024).
astrocytic tumor (1 paper, 2020). A glial tumor of the brain or spinal cord showing astrocytic differentiation. "Expression of S100 and PCNA were both indicated to be significantly differed in astrocytic tumors of different types and grades." (PMID 33585189, 2020).
autoimmune hypophysitis (1 paper, 2017). "When immunostained for proliferating cell nuclear antigen (PCNA), a protein expressed by cells that are actively duplicating DNA prior to cell division, pituitary sections from mice that developed experimental autoimmune hypophysitis showed more proliferating cells than CFA-immunized controls." (PMID 28262761, 2017). "To examine whether infiltrating T cells and B cells were proliferating in the mouse pituitaries in the later stage of autoimmune hypophysitis, we immunostained the pituitary sections from mid-late disease for PCNA, plus CD3 or B220." (PMID 28262761, 2017).
Azoospermia (1 paper, 2023). Absence of any measurable level of sperm,whereby spermatozoa cannot be observed even after centrifugation of the semen pellet. "Meanwhile, RT-qPCR results showed that transfected miR-143-3p mimic into Sertoli cells significantly inhibited the expression of proliferating cell nuclear antigen (PCNA) and B cell leukemia/lymphoma 2 (BCL2), which are markers of azoospermia and cell proliferation." (PMID 37240155, 2023).
CAEBV infection (1 paper, 2006). "Eventually, we found several genes with expression levels significantly higher in cell lines established from NK/T-cell lymphoma than those from CAEBV infection: FGF14, PDCD4, PCNA, MAP2K4, ITGAX and AKAP2 were preferentially expressed in SNK/T cells established from nasal NK/T lymphoma." (PMID 16449999, 2006).
cardiac arrest (1 paper, 2024). Cessation of breathing and/or cardiac function. "The physiological significance of the increased number of twin-nuclei as well as the Ki67+/PCM1+ and PCNA+/PCM1+ nuclei in and the remodelling cardiomyocytes after cardiac arrest thus needs further investigation." (PMID 38902373, 2024). "However, co-expression of PCNA and PCM1 in cardiomyocyte nuclei was found only in the cardiac arrest group (Fig. 4a1–a3)." (PMID 38902373, 2024). "Furthermore, co-expression of PCNA and Ki67 with PCM1 was only found in the cardiac arrest group in the AVj." (PMID 38902373, 2024).
carotid atherosclerosis (1 paper, 2019). A thickening and loss of elasticity of the walls of carotid arteries that occur with formation of atherosclerotic plaques. "In contrast, Uox‐KO mice with carotid atherosclerosis showed severe neointimal changes in histology staining consistent with increases in intimal area and increases in proliferating cell nuclear antigen (PCNA)‐ and F4/80‐positive cells." (PMID 30690853, 2019).
cerebrovascular diseases (1 paper, 2022). "In the present study, TriL treatment showed a dose-dependent inhibitory effect on carotid artery ligation-induced intimal hyperplasia and reduced PCNA expression in the neointima, which implies TriL may have therapeutic potential for cerebrovascular diseases." (PMID 36361610, 2022).
cervix neoplasms (1 paper, 2008). "With PCNA, we established a proliferative rate which tended to be greater in relation to the progression of the cervix neoplasms." (PMID 18786253, 2008).
choriocarcinoma (1 paper, 2023). An aggressive malignant tumor arising from trophoblastic cells.
chronic asthma (1 paper, 2019). An asthma that is characterized by the development of persistent airway inflammation and recurrent attacks of breathlessness and wheezing, which vary in severity and frequency. "In support, using a guinea pig model of chronic asthma, Dekkers and colleagues showed that treatment with YIGSR fully reversed the expression levels of the proliferative marker, PCNA, in ovalbumin-challenged mice." (PMID 31289310, 2019).
chronic gastritis (1 paper, 2015). Inflammation of the stomach that is chronic in nature. "In one study, immunohistochemical staining of proliferating cell nuclear antigen (PCNA) was performed in chronic gastritis patients." (PMID 26583078, 2015).
chronic lymphocytic leukaemia (1 paper, 2005). "Interestingly, our group previously showed that PCNA over-expression was associated with resistance to chemotherapy AML and chronic lymphocytic leukaemia." (PMID 15642167, 2005).
chronic myeloid leukemia (1 paper, 2016). "Notably, PCNA subcellular localization was also examined in K562 cells which are cells of erythroleukemia type derived from a patient with chronic myeloid leukemia and are positive for bcr:abl fusion gene." (PMID 27759041, 2016).
coccidiosis (1 paper, 2016). A parasitic infection caused by Coccidia. "The number of PCNA positive signal cells was also increased in the duodenum epithelium by coccidiosis-challenged." (PMID 27050279, 2016).
colorectal adenoma (1 paper, 2024). An adenoma that arises from the colon or rectum. "The PCNA protein plays an important role in CRC progression and can be used as an additional marker of the malignant transformation risk of colorectal adenomas since it correlates with the dysplasia degree and tumor size." (PMID 39063041, 2024).
Cushing syndrome (1 paper, 2008). Cushing's syndrome (CS) encompasses a group of hormonal disorders caused by prolonged and high exposure levels to glucocorticoids that can be of either endogenous (adrenal cortex production) or exogenous (iatrogenic) origin. "To conquer such difficulties, we conducted a survey of human genome and tumor genetics and identified several useful (potential) markers such as the expression profiles of cyclin E, P27kip1, FHIT, Bax, Fas, FasL, PCNA, hTERT and Ki-67 for types of Cushing's syndrome." (PMID 18366613, 2008). "However most of Cushing's syndrome are benign tumors and, as such, it is reasonable that FHIT and PCNA are dominant features to diagnose different types of hypercortisolism in the intelligent machine." (PMID 18366613, 2008).
demyelination (1 paper, 2019). "However, the fraction of dividing OPCs (% NG2+/PCNA+ among total NG2+) was significantly increased, while that of non-dividing OPCs was significantly decreased in the lysolecithin-induced demyelination during pregnancy when compared to those seen in either virgin or postpartum rats (p < 0.05)." (PMID 31118452, 2019).
desmoid tumor (1 paper, 2015). A desmoid tumor (DT) is a benign, locally invasive soft tissue tumor associated with a high recurrence rate but with no metastatic potential. "Increased PCNA staining was also apparent in other tumor types that we analyzed by immunostaining, namely the epidermoid cysts and desmoid tumors." (PMID 26097888, 2015).
diffuse astrocytoma (1 paper, 1997). A low-grade (WHO grade II) astrocytic neoplasm. "Univariate analysis in the group of diffuse astrocytomas showed that older age, high histological grade, high PCNA labelling index (LI) and high AgNOR score were associated with reduced overall survival (P < 0.05)." (PMID 9155045, 1997).
endocervical adenocarcinoma (1 paper, 2025). An adenocarcinoma that arises from the endocervix. "Inversely, high expressionof PCNA was linked to improved prognosis in patients with cervicalsquamous cell carcinoma and endocervical adenocarcinoma (CESC) (HR= 0.58, p = 0.023) and thymoma (THYM)(HR = 0.09, p = 0.026)." (PMID 40657100, 2025).
endometrial adenocarcinomas (1 paper, 2007). "In endometrial adenocarcinomas the PCNA index has been found to correlate with tumor grade, depth of myometrial invasion, and recurrence risk, and it has been suggested that PCNA staining can be used as a method of pre-operative identification of high risk patients." (PMID 19690652, 2007).
epidermoid cysts (1 paper, 2015). "To further examine whether TALEN-driven apc mutation affects cell proliferation, we performed proliferating cell nuclear antigen (PCNA) analysis on sections from intestines, epidermoid cysts, and the desmoid and hind limb tumors." (PMID 26097888, 2015).
Epstein-Barr virus infection (1 paper, 2017). An infection that is caused by Epstein-Barr virus. "BPLF1 promotes Epstein-Barr virus infection and pathogenesis by mimicking USP1, deubiquitinating PCNA to disrupt the recruitment of DNA polymerases such as polη, and thus impeding DNA damage repair." (PMID 29091922, 2017).
esophageal tumor (1 paper, 2017). "Both nonproliferative ZS esophagus (after a 6-week dietary regimen) and non-ESCC-bearing ZS rat esophagus (from an esophageal tumor study) showed few PCNA-positive nuclei, mostly restricted to basal cell layer." (PMID 29137232, 2017).
eye tumor (1 paper, 2018). "Downregulation of PCNA and dpa led to significant developmental defects on the fly’s retina, preventing their study in the eye tumor models." (PMID 30144809, 2018).
Fibroadenoma (1 paper, 2007). A benign tumor of the breast characterized by the presence of stromal and epithelial elements. "They found that the PCNA expression was low in standard fibroadenoma fibroblasts and that, as the stromal cellularity increased (as in hypercellular fibroadenomas and phyllodes tumors), there was increased PCNA expression." (PMID 18094894, 2007).
fibrosarcoma (1 paper, 2017). A malignant mesenchymal fibroblastic neoplasm affecting the soft tissue and bone. "In spontaneous feline fibrosarcomas the higher PCNA LI also positively correlates with the higher tumor grade (r = 0.4837, p < 0.05)." (PMID 28651614, 2017). "In spontaneous feline fibrosarcomas PCNA LI mean values were: 86.6 and 75.2% for grade III and grade II, respectively." (PMID 28651614, 2017). "On the other hand, tumor grade positively correlates with PCNA expression, what indicates that PCNA may be a better marker to assume tumor grade in feline fibrosarcomas, in opposed to Ki-67." (PMID 28651614, 2017). "The results obtained indicate that PCNA may be helpful to evaluate the tumor grade, better than Ki-67, for feline fibrosarcomas." (PMID 28651614, 2017). "In our study PCNA LI was much higher for fibrosarcomas from both cell lines than Ki-67 LI." (PMID 28651614, 2017). "There was a statistically significant difference (p < 0.05) in PCNA immunoreactivity between grade II and grade III spontaneous feline fibrosarcomas." (PMID 28651614, 2017). "We did not have grade I fibrosarcomas, which remains unable to correlate with Ki-67 and PCNA immunostaining." (PMID 28651614, 2017).
follicular thyroid cancer (1 paper, 2016). "In follicular thyroid cancer cells, leptin had more dramatic effects in gene expression than those of OB3; for example leptin increased the expression of PCNA and c-Myc in FTC236 cells but decreased the expression of PCNA, c-Myc and MCL-1 in FTC238 cells." (PMID 27050378, 2016).
GEJ adenocarcinoma (1 paper, 2013). "Given that PAK1 has been reported to regulate cell proliferation in several cancers, we further examined if PAK1 is correlated with PCNA, a cell proliferation marker, in GEJ adenocarcinoma." (PMID 24236193, 2013).
Granuloma (1 paper, 2021). A compact, organized collection of mature mononuclear phagocytes, which may be but is not necessarily accompanied by accessory features such as necrosis. "In the present study, we analyzed the number of AEC2, collagen deposition, expression of p21 and PCNA in normal alveoli, alveolitis (consisting of macrophages and hypertrophic AEC2), and silicotic granulomas." (PMID 34426759, 2021).
Graves disease (1 paper, 2021). Graves' disease is an autoimmune disorder that leads to overactivity of the thyroid gland (hyperthyroidism).It is caused by an abnormal immune system response that causes the thyroid gland to produce too much thyroid hormones. "Previous studies in a murine model of Graves’ disease have shown that diosgenin can inhibit the proliferation of thyroid cells by inhibiting the expression of IGF-1, NF-κB, cyclin D1, and PCNA and alleviate goitre." (PMID 33737640, 2021).
helminth infection (1 paper, 2024). "Significant increase in the number of PCNA-positive MCs at the site of helminth infection was documented in some papers." (PMID 38193283, 2024).
hematoma (1 paper, 2018). A hematoma is a collection of blood from a vascular structure into an extravascular space. "Following ICH, lactate accumulated around the hematoma; the numbers of PCNA+/vWF+ nuclei and PCNA+/DCX+ cells were significantly increased compared with the numbers in the Sham group." (PMID 29980670, 2018).
hepatoblastoma (1 paper, 2025). Hepatoblastoma (HB) is a malignant hepatic tumor and is the most common pediatric liver cancer. "The activated ERK1/2 enters the nucleus and continuously activates Cyclin D1 and proliferating cell nuclear antigen (PCNA), disrupting the balance of cell cycle regulation and leading to abnormal proliferation of hepatoblastoma cells." (PMID 41018265, 2025).
herpesvirus infections (1 paper, 2025). "Multiple studies have demonstrated that regulation of PCNA and its post-translational modifications are important for other herpesvirus infections." (PMID 40130902, 2025). "It is possible that herpesvirus infections commonly induce mUb-PCNA, but its significance to infection varies among different viruses." (PMID 40130902, 2025).
Hydrocephalus (1 paper, 2022). Hydrocephalus is an active distension of the ventricular system of the brain resulting from inadequate passage of CSF from its point of production within the cerebral ventricles to its point of absorption into the systemic circulation. "We observed a significant decrease of proliferative cells in the ASVZ in the pigs with induced hydrocephalus since the total number of PCNA+ cells was lower compared to the sham control." (PMID 35193620, 2022).
hypercortisolism (1 paper, 2008). "The clinical significance of this medical decision system using expression levels of FHIT, Ki-67 and PCNA and 5 related factors is that this system concurred the difficulties of diagnosing hypercortisolism of various adrenocortical diseases." (PMID 18366613, 2008). "Multivariate ordinal logistic regression analysis found that only FHIT and PCNA are strongly related factors of hypercortisolism of various adrenocortical diseases." (PMID 18366613, 2008). "Found in this study, there are some rules in expression levels of FHIT, Ki-67, and PCNA in hypercortisolism of various adrenocortical diseases." (PMID 18366613, 2008). "This study found there are some rules in expression levels of FHIT, Ki-67, and PCNA in hypercortisolism of various adrenocortical diseases." (PMID 18366613, 2008). "The results suggested that FHIT and PCNA are the more closely related factors for diagnose of hypercortisolism of various adrenocortical diseases." (PMID 18366613, 2008). "The correlation between the FHIT and hypercortisolism was negative, the correlation between the PCNA and hypercortisolism was positive." (PMID 18366613, 2008).
Hyperkalemia (1 paper, 2022). An abnormally increased potassium concentration in the blood. "To test if the increase in PCNA expression by aldosterone could be secondary to hypokalemia, we further assessed kidneys from mice that were infused with amiloride + aldosterone (had mild hyperkalemia) and mice that were fed a low K+ diet for 6 days (were hypokalemic)." (PMID 35557966, 2022).